PRDX2 (peroxiredoxin 2)
Diseases named in the same sentence as PRDX2 in open-access papers (continued):
Sharing a sentence is not in itself a finding about the gene and the disease.
breast carcinoma (continued). "Our studies demonstrated that a panel of biomarkers including cathepsin D, CK19, nucleophosmin and peroxiredoxin 2 would be applied as a set of indicators for breast cancer relapse, and they could also represent potential therapeutic targets under sufficient validation." (PMID 32846884, 2020). "Likewise, when a range of breast cancer cell lines were analysed by western blotting, we noticed that PRDX1 and PRDX2 protein content is highly upregulated in breast cancer cells, as compared to primary human mammary epithelial cells HMEC and non-malignant, mammary tissue-derived MCF-10A cell line." (PMID 30287919, 2018). "Using a proteomic approach, we could show that several antioxidant proteins, for example, SOD1, PRDX2, and PARK7, were downregulated in the normo-sensitive patients and some antioxidant proteins, for example, BLVRB and PRDX2, were upregulated in the radiosensitive breast cancer patients." (PMID 29951164, 2018). "Among the proteins commonly identified across serum and saliva, PRDX2, LG3BP and TSP1 are promising for further investigation to distinguish the benign from the malignant stage of breast cancer in a larger cohort." (PMID 36835577, 2023). "The highest frequency of antibodies to an individual TAA in breast cancer was against A1AT (83.3%) and TPI1 (66.7%), followed by PPIA (58.3%) and PRDX2 (50%)." (PMID 33096879, 2020). "ELISA was performed to confirm the altered expression levels of PRDX2, PRDX6, CTSB and CTSD in the serum among the breast cancer patients and healthy volunteers as a representative sample in order to validate the serum levels." (PMID 24932247, 2014). "The authors examined by ELISA the presence of AAbs to five individual TAAs, PPIA, PRDX2, FKBP52, HSP-60, and MUC1, in sera from 60 breast carcinoma patients, 82 breast carcinoma in situ patients, and 93 healthy controls." (PMID 21423545, 2011). "Noh and colleagues reported that PRDX1, PRDX2 and PRDX3 were overexpressed in breast cancer tissues, suggesting that PRDXs had a proliferative effect and might be related to cancer development or progression." (PMID 17980029, 2007). "Our current study indicates the superior role for PRDX1, but not PRDX2, in curtailing oxidative stress by breast cancer cells and suggests that this molecule could be further examined as a potential therapeutic target in this disease." (PMID 30287919, 2018). "Moreover, in the case of control samples, we found overexpression of the proteins: PRDX2, PRDX5 and AIFM1 involved in ROS; TUSC2 in PMM; ALKBH7, RHOT1, SAMM50, IMMT and HSPA9 in the MMO; and FUNDC2 in MIT compared to luminal A and basal-like breast cancer tumors." (PMID 35327574, 2022). "Taken together, these findings imply again that mainly PRDX1, but not PRDX2, plays a substantial role in exogenous H2O2 metabolism in breast cancer cells and, hence, is protecting these cells against toxicities of the H2O2-stimulated oxidative stress." (PMID 30287919, 2018). "Hereby, similarly to MCF-7, we observed a significant decrease in the growth rate of ZR-75-1 breast cancer cells harboring the shRNA against PRDX1 (ZR-75-1 shPRDX1), but not PRDX2 (ZR-75-1 shPRDX2), as compared to the controls (ZR-75-1 parental and shNTC)." (PMID 30287919, 2018). "Additional associations with MFI found for thioredoxin and downstream factors of the thioredoxin pathway, including PRDX2, RRM2, HIF1A and VEGF, confirm the importance of the thioredoxin system in breast cancer regardless of its ROS-related or unrelated roles." (PMID 20584310, 2010). "Karihtala and colleagues observed that staining for PRDX2 and PRDX6 was negative in half of breast cancer cases, whereas PRDX1, PRDX3, PRDX4 and PRDX5 showed stronger expression levels." (PMID 17980029, 2007).
gastric cancer (21 papers, 2020 to 2025). A primary or metastatic malignant neoplasm involving the stomach. "For gastric cancer, higher PRDX2 expression is linked to advanced TNM stages, lymph node metastasis, and a poorer prognosis." (PMID 40645965, 2025). "Celastrol treatment of mice implanted with gastric cancer cells also inhibited tumor growth, associated with Prdx2 inhibition and increased ROS." (PMID 32929349, 2020). "A recent study showed that PRDX2 was significantly increased in tissues and cell lines, and the overexpression of PRDX2 was associated with the poor clinical outcomes of gastric cancer." (PMID 32908916, 2020). "To explore whether Celastrol inhibits gastric cancer growth and whether such activities are associated with Prdx2 targeting, we first carried out modified organoid cultures." (PMID 32929349, 2020). "Gastric cancer cells adopt PRDX2 (peroxiredoxin 2) to eliminate ROS and avoid apoptosis, acquiring resistance to cisplatin chemotherapy." (PMID 40847302, 2025). "CircDIDO1 downregulation leads to a decrease in the RING box protein-1 (RBX1)-mediated ubiquitination and degradation of PRDX2, thereby stabilizing PRDX2 protein and enhancing the antioxidant capacity of gastric cancer cells." (PMID 40227215, 2025). "Previous studies have reported elevated PRDX2 expression in several types of cancer cells, including lung, liver, renal, and gastric carcinoma." (PMID 35744062, 2022). "Prdx2 has a high expression level in various cancers, such as lung, colorectal, and gastric cancers." (PMID 34679770, 2021). "A high level of PRDX2 has been demonstrated as a poor prognostic marker in cisplatin-resistant gastric cancer." (PMID 34384442, 2021). "Prdx2 has been reported to have a high expression level in various cancers, including in lung, colorectal, and gastric cancers." (PMID 34679770, 2021). "In both culture and mouse studies, Celastrol afforded gastric cancer cytotoxicity through Prdx2 and ROS modulation." (PMID 32929349, 2020). "The overexpression of Prdx2 rendered leukemia and stomach cancer cells resistant to various chemotherapeutic agents, and the downregulation of Prdx2 sensitized head and neck cancer cells to radiation and gastric carcinoma cells to cisplatin." (PMID 33182509, 2020). "Functional tests demonstrated that Celastrol limits gastric cancer cells, at least in part, through targeting Prdx2." (PMID 32929349, 2020). "Our results show that bio-Celastrol binds to Prdx2 protein in lysates from both gastric cancer cells in culture and gastric cancer tissues generated in mice." (PMID 32929349, 2020). "Based on our cell culture studies, we expected a reversal of Celastrol activity in gastric cancer cells with Prdx2 overexpression (O/E)." (PMID 32929349, 2020). "Previous studies have shown that PRDX2 expression is upregulated in different types of tumors such as gastric cancer and esophageal carcinoma." (PMID 32908916, 2020). "To validate Prdx2 as a potential therapeutic target of gastric cancer, we assessed Prdx2 transcript levels in biopsy specimens obtained from patients with gastric cancer." (PMID 32929349, 2020). "Inhibition of Prdx2 by Celastrol increased cellular ROS levels and led to ROS-dependent endoplasmic reticulum stress, mitochondrial dysfunction, and apoptosis in gastric cancer cells." (PMID 32929349, 2020). "Using human gastric cancer specimens and analyzing gene databases, we show that Prdx2 is overexpressed in gastric cancer." (PMID 32929349, 2020). "Our detailed investigation shows that Celastrol enhances ROS generation in gastric cancer cells by inhibiting Prdx2, which in turn initiates ER stress and mitochondrial dysfunction and results in apoptotic cell death." (PMID 32929349, 2020). "Bioinformatics analysis has revealed that low Prdx2 expression was strongly correlated with poor survival in stomach cancer and silencing of Prdx2 enhanced lung metastasis in melanoma." (PMID 33182509, 2020).
gastric cancer (continued). "We also found that Prdx2 mRNA and protein levels were elevated in human gastric cancer biopsy specimens." (PMID 32929349, 2020). "We found that Celastrol directly binds to and inhibits the activity of Prdx2, resulting in increased ROS levels and apoptotic death in gastric cancer cells." (PMID 32929349, 2020). "On the contrary, PRDX2 acted as an oncogene in many malignant tumors, including prostate cancer, gastric cancer, esophageal carcinoma, and cervical cancer." (PMID 32908916, 2020). "We confirmed the involvement of Prdx2 in Celastrol-mediated gastric cancer cell death by modulating the levels of Prdx2." (PMID 32929349, 2020). "Celastrol directly binds to and inhibits Prdx2 activity, which augments ROS accumulation to induce ER stress, mitochondrial dysfunction, and apoptosis in gastric cancer cells." (PMID 32929349, 2020). "To determine this, we used the Kaplan-Meier Plotter to stratify gastric cancer based on Prdx2 into high and low." (PMID 32929349, 2020). "Our results show that 15 of 17 samples analyzed had at least a 2x fold increase in Prdx2 in gastric cancer samples compared to patient-matched, tumor-adjacent samples." (PMID 32929349, 2020). "For example, ROS and oxidative DNA damage may have anticancer effects in gastric cancer cells because the antioxidant enzyme peroxiredoxin 2 (PRDX2) is suppressed or gastrokine 2 (GKN2) is overexpressed." (PMID 38086844, 2023). "In gastric cancer, patients with higher PRDX2 expression had significantly decreased survival compared to those with lower expression; additionally, in vitro knockdown of PRDX2 significantly suppressed cancer cell proliferation and metastasis." (PMID 35744062, 2022). "Analysis of human gastric cancer also showed increased Prdx2 levels and correlation with survival." (PMID 32929349, 2020). "Therefore, our studies discovered a precise target of Celastrol and highlighted the importance of targeting Prdx2 in gastric cancer treatment." (PMID 32929349, 2020). "The findings also highlight Prdx2 as a potential target for the treatment of gastric cancer." (PMID 32929349, 2020). "Studies have also shown that celastrol directly binds to peroxiredoxin-2 (Prdx2) and inhibits its enzyme activity, increasing ROS levels and resulting in ROS-dependent endoplasmic reticulum (ER) stress, mitochondrial dysfunction, and apoptosis in gastric cancer cells." (PMID 39494324, 2024). "Besides, studies have reported that tripterine inhibits PRDX2, leading to increased intracellular ROS levels, which induces ROS-dependent endoplasmic reticulum stress, mitochondrial dysfunction, and apoptosis in gastric cancer cells." (PMID 37758743, 2023). "Besides, PRDX2 is reported to be upregulated in many other tumors, such as gastric cancer, and lung cancer, suggesting that PRDX2 may be a promising prognostic biomarker." (PMID 34117220, 2021). "Therefore, the antioxidant Prdx2 protein may represent an excellent target to pursue for the development of therapies for gastric cancer patients." (PMID 32929349, 2020). "For example, triptolide induces reactive oxygen species (ROS) accumulation by directly binding to peroxiredoxin 2 (PRDX2), leading to both apoptosis and cytoprotective autophagy in gastric cancer cells." (PMID 41179291, 2025). "Validation of the RIPK genes through GEPIA identified 8 genes (NRP1, MNX1, SSRP1, PRDX2, PLRG1, LGALS4, SNX5 and FXYD3) which are highly expressed in stomach cancer were significantly down-regulated in PRU treated samples." (PMID 35831348, 2022). "Specifically, 8 genes (NRP1, MNX1AS1, SSRP1, PRDX2, PLRG1, LGALS4, SNX5 and FXYD3) were found to be highly expressed in stomach cancer tissues compared to normal tissues." (PMID 35831348, 2022). "Specifically, 8 genes NRP1, MNX1, SSRP1, PRDX2, PLRG1, LGALS4, SNX5 and FXYD3) which are highly expressed in stomach cancer were significantly down-regulated in PRU treated samples." (PMID 35831348, 2022).
gastric cancer (continued). "Gene expression profiling using oligonucleotide arrays on 22 gastric cancer tissues revealed an increase in the expression of the genes LGALS4, FXYD3, SSRP1, and PRDX2 (Reference: GSE2685)." (PMID 35831348, 2022).
melanoma (17 papers, 2007 to 2026). A malignant, usually aggressive tumor composed of atypical, neoplastic melanocytes. "Accordingly, it has been recently shown that NRAS-mutated melanomas have lower PRDX2 (peroxiredoxin 2) expression compared to BRAF-mutated melanomas, which is correlated with lower survival and higher malignancy in patients." (PMID 40141318, 2025). "Proliferation and migration are promoted by melanoma PRDX2 expression, which is also linked to EMT and β-catenin signaling." (PMID 38178861, 2023). "Reduced PRDX2 expression in human melanoma cells is associated with increased proliferation and migration via PRDX2 suppression of Src/ERK signaling, which also increased E-cadherin and retention of β-catenin at the adherens junction." (PMID 34067095, 2021). "Decreased level of peroxiredoxin 2 causes the accumulation of intracellular ROS, which in turn results in the disruption of e-cadherin/β-catenin complexes and leads to the promotion of melanoma cell migration and metastasis." (PMID 32846884, 2020). "Overexpression of PRDX2 may either promote cancer growth or inhibit cancer development depending on the cancer context and the different mutations cooccurring in the cancer cells, among which are the melanomas." (PMID 40932790, 2025). "The expression of PRDX1 was higher than that of PRDX2 in melanoma cells and more similar to that of MITF than that of PRDX2." (PMID 38790661, 2024). "Downregulation of PRDX2 in melanoma cells is related to more production of ROS, proliferation, and migration." (PMID 38790661, 2024). "We found PRDX1 enriched in neurons more than PRDX2, while some populations of melanoma cells express more PRDX2 than PRDX1." (PMID 38790661, 2024). "PRDX1 shows significant co-expression with MITF in melanoma patients, with PRDX2 showing a tendency towards mutual exclusivity." (PMID 38790661, 2024). "PRDX2 has been shown to inhibit melanoma proliferation and migration in cell lines and metastasis in a mouse xenograft model." (PMID 35326683, 2022). "As a tumor suppressor, PRDX2 is expressed in normal melanocytes, but its expression is lost in methylated melanomas." (PMID 34490047, 2021). "PRDX2 was significantly downregulated in melanoma, and the decreased expression resulted in inhibiting proliferation and migration of melanoma cells." (PMID 32908916, 2020). "Silencing Prdx2 suppresses the growth of prostate cancer cells by inducing cell-cycle arrest at the G1 phase 42, and lung metastasis of melanoma cells." (PMID 32929349, 2020). "Among these genes, Peroxiredoxin‐2 (Prdx2) is expressed in natural melanocytes, and its expression in the melanoma is vanished by methylation." (PMID 32232956, 2020). "Downregulation of Prdx2 has been reported to correlate with increased proliferative and migratory activities in melanoma cell lines and in vivo melanoma models." (PMID 33182509, 2020). "Several studies have reported that PRDX2 is silenced by the promoter hyper-methylation in melanoma and miR-200c in lung cancer, although these findings are not sufficient to interpret the mechanisms underlying the upregulation of PRDX2 in CRC." (PMID 29258530, 2017). "On the one hand, a decreased expression of PRDX2 contributes to enhanced proliferation, motility and metastasis of melanoma cells." (PMID 29258530, 2017). "Interestingly, PRDX2 can interfere with the cellular oxidative metabolism, and it is depleted in vemurafenib-resistant melanomas." (PMID 40141318, 2025). "In fact, it was demonstrated that PRDX2 prevents metastasis by increasing E-cadherin/β-catenin complexes, and that PRDX2 is downregulated in melanomas and could be restored by a demethylating agent." (PMID 38790661, 2024). "Additionally, the role of PRDX2 in preventing invasion in BRAF-mutant melanoma has been described in a heterogenous population, but its roles in heterogeneity, resistance, and pigmentation are not known." (PMID 38790661, 2024).
melanoma (continued). "However, there are conflicting reports of the decreased expressions of PRDX1 and PRDX2 in at least a subset of melanomas." (PMID 35326683, 2022). "Similarly, compared with normal tissues, another typical 2-Cys antioxidant enzyme, peroxiredoxin 2 (PRDX2), is downregulated in melanoma tissues and upregulated in the colon, cervical, lung, and other malignancies." (PMID 34490047, 2021). "Our results suggested that PRDX1 and PRDX2 may play distinct roles in melanoma heterogeneity." (PMID 38790661, 2024). "However, there may be a compensatory relationship between PRDX2 and 6 in Xiphophorus melanoma that has yet to be characterized or that these antioxidant proteins respond to different degrees of oxidative stress." (PMID 34067095, 2021). "Moreover, PRDXs are differentially expressed in patients during melanoma progression and decreased expression of PRDX1 and PRDX2 is a biomarker in melanoma compared to nevus." (PMID 38790661, 2024). "As PRDX2 regulation of oxidative stress may be different in Xiphophorus compared to human melanoma, this could mean that Xmrk signaling may not integrate PRDX2 function." (PMID 34067095, 2021). "Considering that PRDX1 and PRDX2 belong to typical 2‐Cys PRDXs, and have similar active sites 8, we therefore hypothesize that PRDX1 may also play important roles in the suppression of melanoma development." (PMID 27653015, 2017). "de Souza and colleagues observed decreases in the expression of PRDX2 and PRDX6 proteins in murine melanoma line Tm1 compared with Tm5 from nontumor cells." (PMID 17980029, 2007). "In Xiphophorus malignant melanoma tissue, oxidative stress increases and is correlated with upregulation of the antioxidative proteins, glutathione-S-transferase mu3 (GST mu3) and peroxiredoxin-6 (PRDX6), but not PRDX2, which was subject to a non-significant increase." (PMID 34067095, 2021).